GNB3 (G protein subunit beta 3)
Description:
Guanine nucleotide-binding proteins (G proteins) are involved as a modulator or transducer in various transmembrane signaling systems. The beta and gamma chains are required for the GTPase activity, for replacement of GDP by GTP, and for G protein-effector interaction.
Synonyms: CSNB1H; HG2D
Tractability: Antibody: its Gene Ontology location is reachable by antibodies, with high confidence; the Human Protein Atlas places it where antibodies can reach. PROTAC: ubiquitination databases record sites on it.
Safety:
Unwanted effects reported when the protein is acted on. In parentheses: how it was acted on, where the effect was seen, and who reports it.
diabetes mellitus (source: ClinPGx)
increase in pulse rate (source: ClinPGx)
less of an increase in pulse rate (source: ClinPGx)
weight gain (source: ClinPGx)
Gene: Protein-coding gene on chromosome 12 (6,839,954 to 6,847,393, forward strand). Ensembl gene ENSG00000111664.
Subcellular location (Human Protein Atlas): Plasma membrane; Golgi apparatus
Pathways (Reactome):
Signal Transduction: Ca2+ pathway; Extra-nuclear estrogen signaling; G alpha (12/13) signalling events; G alpha (i) signalling events; G alpha (q) signalling events; G alpha (s) signalling events; G alpha (z) signalling events; G beta:gamma signalling through BTK; G beta:gamma signalling through CDC42; G beta:gamma signalling through PI3Kgamma; G beta:gamma signalling through PLC beta; G-protein activation; GPER1 signaling; Glucagon-type ligand receptors
Hemostasis: ADP signalling through P2Y purinoceptor 1; ADP signalling through P2Y purinoceptor 12; Prostacyclin signalling through prostacyclin receptor; Thrombin signalling through proteinase activated receptors (PARs); Thromboxane signalling through TP receptor
Metabolism: Adrenaline,noradrenaline inhibits insulin secretion; Glucagon signaling in metabolic regulation; Glucagon-like Peptide-1 (GLP1) regulates insulin secretion
Neuronal System: Activation of G protein gated Potassium channels; Inhibition of voltage gated Ca2+ channels via Gbeta/gamma subunits; Presynaptic function of Kainate receptors
Metabolism of proteins: Cooperation of PDCL (PhLP1) and TRiC/CCT in G-protein beta folding; Synthesis, secretion, and inactivation of Glucagon-like Peptide-1 (GLP-1)
Cellular responses to stimuli: High laminar flow shear stress activates signaling by PIEZO1 and PECAM1:CDH5:KDR in endothelial cells
Disease: ADORA2B mediated anti-inflammatory cytokines production
Sensory Perception: Sensory perception of sweet, bitter, and umami (glutamate) taste
Transport of small molecules: Vasopressin regulates renal water homeostasis via Aquaporins
Gene Ontology:
Molecular function: GTPase binding; protein binding; GTPase activity; signaling receptor complex adaptor activity; spectrin binding
Biological process: cell volume homeostasis; regulation of cholesterol metabolic process; regulation of fat cell differentiation; regulation of feeding behavior; regulation of gene expression; regulation of glucose metabolic process; regulation of hormone metabolic process; regulation of locomotion involved in locomotory behavior; regulation of phospholipid metabolic process; regulation of triglyceride metabolic process; G protein-coupled receptor signaling pathway; regulation of blood pressure; signal transduction
Cellular component: extracellular exosome; cytosol; plasma membrane; cell body; dendrite; heterotrimeric G-protein complex
Genetic constraint (gnomAD): Loss-of-function variants: 31 observed, 39.02 expected, observed/expected ratio (o/e) 0.79, 90% interval 0.6 to 1.07. The upper end of that interval is the gene's LOEUF score, 1.07, which puts it in group 4 of 6, group 1 being the genes least tolerant of losing a copy. Missense variants: 368 observed, 425.08 expected, observed/expected ratio (o/e) 0.87, 90% interval 0.79 to 0.94. Synonymous variants: 159 observed, 165.81 expected, observed/expected ratio (o/e) 0.96, 90% interval 0.84 to 1.09.
Homologues: Orthologues: chimpanzee GNB3 (100% identical), macaque GNB3 (100% identical), rabbit GNB3 (98% identical), pig GNB3 (97% identical), mouse Gnb3 (97% identical), guinea pig GNB3 (97% identical), rat Gnb3 (96% identical), dog GNB3 (90% identical), tropical clawed frog gnb3 (88% identical), Caenorhabditis elegans gpb-1 (81% identical), zebrafish gnb3a (80% identical), Drosophila melanogaster Gbeta13F (77% identical), and 1 more. Paralogues in human: GNB1 (83% identical), GNB2 (81% identical), GNB4 (80% identical), GNB5 (53% identical).
Diseases named in the same sentence as GNB3 in open-access papers:
GNB3 is named in the same sentence as 97 diseases in open-access papers, as found by Europe PMC text mining. Sharing a sentence is not in itself a finding about the gene and the disease. The quoted sentences say what the papers report.
Hypertension (34 papers, 2005 to 2025). The presence of chronic increased pressure in the systemic arterial system. "While the c.825C > T allele of GNB3 has been associated with many phenotypes, only obesity and hypertension have been affirmed by meta-analysis." (PMID 39743506, 2025). "T allele polymorphisms in the GNB3 gene are associated with increased intracellular signaling, increased risk of hypertension, low plasma renin, and cardiac remodeling." (PMID 37089887, 2023). "Among the downregulated genes, GNB3 is associated with hypertension and SENP2 with newborn health issues." (PMID 38681774, 2023). "Recently, changes of cytosine to thymidine (C825T) in the β3 subunit of the G protein gene (GNB3) have been discovered in individuals with essential hypertension and considered as a candidate mutation for arterial hypertension." (PMID 37201134, 2023). "Another study reported that FTO rs8050136, rs9939609 and rs9926289, and GNB3 rs1129649 and rs5443 were positively associated with essential hypertension in an Indian population." (PMID 37238719, 2023). "GNB3 is associated with obesity, and enhanced GNB3 signaling increases the risk of brain disease, obesity, hypertension and coronary heart disease." (PMID 36230385, 2022). "Another single-nucleotide polymorphism of GNB3, the rs2301339, was linked to the young-onset hypertension in the Chinese population considering 992 young-onset hypertensive cases and 992 matched controls." (PMID 36077181, 2022). "The GNB3 C825T polymorphism is a marker for the treatment of hypertension, and its phenotype has enhanced sodium-proton reverse motility activity." (PMID 34040073, 2021). "Similar observations have been reported with the variants -217A, 825T, and -246G in the AGT, GNB3, and ENaCα genes, respectively, which are associated with hypertension." (PMID 31790415, 2019). "In the previous studies, the relation between GNB3, sodium intake, and the risk for developing hypertension were obtained mainly by cross-sectional designs for establishing causal relationships which cause the most important threat against validity." (PMID 29848945, 2018). "The study aims to evaluate joint effects of GNB3 polymorphisms and sodium consumption on the development of hypertension." (PMID 29848945, 2018). "Participants with high sodium intake and GNB3 (CT and CC combined) increased the risk of hypertension significantly with an adjusted odds ratio of 1.51 (95% CI 0.88–2.60)." (PMID 29848945, 2018). "This study assumed that participants with GNB3 TT genotype increased their susceptibility to the effects of dietary sodium consumption on the development of hypertension." (PMID 29848945, 2018). "Population-based and case–control studies in different ethnicities have linked a polymorphism, C825T, in exon 10 of GNB3 gene to hypertension and several additional diseases." (PMID 27462452, 2016). "Several studies have shown that the T allele of the GNB3 rs5443 SNP is associated with a number of health outcomes and other features of MetS including obesity, insulin resistance, dyslipidemia, hypertension." (PMID 27386434, 2016). "The C825T polymorphism (rs5443) of the Guanine Nucleotide-Binding protein subunit β3 (GNB3) gene has been associated with obesity, essential hypertension, atherosclerosis, coronary diseases, and cerebrovascular events, but with some sex-specific effects." (PMID 27990099, 2016). "The G-protein beta 3 subunit (GNB3) C825T polymorphism was detected through a candidate gene approach using cell lines with enhanced G-protein activation from patients with essential hypertension." (PMID 27462452, 2016). "Several epidemiological studies have evaluated the association between the GNB3 C825T polymorphism and hypertension or stroke." (PMID 23799054, 2013). "In our meta-analysis, individual studies on Africans, Asians, and other ethnicities were deficient; therefore, additional evidence regarding the correlation of the GNB3 C825T polymorphism with hypertension or stroke is required." (PMID 23799054, 2013).
Hypertension (continued). "A significant overall association between the GNB3 C825T polymorphism and the risk of hypertension was only detected in the allelic model (OR = 1.07, 95% CI = 1.01–1.13)." (PMID 23799054, 2013). "The FTO alleles rs8050136A (P = 0.014), rs9939609A (P = 0.002), rs9926289A (P = 0.015) and the GNB3 alleles rs1129649C (P = 8.76E–06) and rs5443T (P = 9.45E–10) were associated with increased risk of hypertension." (PMID 23691120, 2013). "Recently, many groups have investigated the relationship between the GNB3 C825T polymorphism and hypertension or stroke; however, the results have been inconclusive." (PMID 23799054, 2013). "Recently, several studies reported that the GNB3 825T polymorphism was associated with an increased risk of hypertension, obesity, metabolic syndrome, atherosclerosis, and diabetes mellitus." (PMID 23799054, 2013). "Interactions between genetic variants of FTO and GNB3 influence clinical parameters to augment hypertension." (PMID 23691120, 2013). "The omnibus global test for both FTO and GNB3 haplotypes showed significant association with hypertension (P<0.0001, each)." (PMID 23691120, 2013). "All models concerning the association of the GNB3 C825T polymorphism and hypertension or stroke were identified using the random effects model for I2>50%, which suggested significant heterogeneity." (PMID 23799054, 2013). "Of the 66 studies, eight compared males and females to assess an association between the GNB3 C825T polymorphism and hypertension." (PMID 23799054, 2013). "The main characteristics of included studies regarding the association between the GNB3 C825T polymorphism and hypertension." (PMID 23799054, 2013). "The main results of meta-analysis of the association between the GNB3 C825T polymorphism and hypertension." (PMID 23799054, 2013). "The genes FTO and GNB3 are implicated in essential hypertension but their interaction remains to be explored." (PMID 23691120, 2013). "Overall, our meta-analytical results showed that the GNB3 825T allele had a weak association with essential hypertension." (PMID 23799054, 2013). "The association of the T allele of the GNB3 C825T polymorphism with arterial hypertension has been confirmed in smaller cohorts." (PMID 22408428, 2012). "Two exonic polymorphisms G460T in α-adducin gene and C825T in GNB3 gene have become a focus of researches and are suggestively associated with hypertension, although this claim is controversial." (PMID 21364877, 2011). "Our overall results suggest null association of α-adducin G460T and GNB3 C825T polymorphisms with hypertension in Chinese but indicate local marginal significance of C825T, as a putative salt-sensitive switch, in southern Chinese." (PMID 21364877, 2011). "These include pathogenic variants of G protein subunits such as the GNB3 gene in hypertension, activating GNAS variants in McCune-Albright’s syndrome, heterozygous inheritance of inactivating GNAS variants in AHO, and PPH resulting from heterozygous LOF GNAS variants." (PMID 39743506, 2025). "For example, a c.825C > T variant of the GNB3 gene encoding Gβ3 may result in alternative splicing that is associated with enhanced signaling in hypertension." (PMID 39743506, 2025). "Recent studies have shown a clear correlation between arterial hypertension and the T allele variant of the GNB3 c.825C > T polymorphism; these results were attributed to the increased activation of G protein-coupled signal transduction in the subgroup of white patients." (PMID 37894940, 2023). "Interactions between genetic variants of FTO and GNB3 influence clinical parameters to augment hypertension, probably by modulating the FTO expression in metabolically relevant tissues such as the hypothalamus and affecting the subsequent translation of key signaling molecules such as GNB3." (PMID 37238719, 2023). "The TT genotype of GNB3 is well known to be associated with arterial hypertension." (PMID 36077181, 2022).
Hypertension (continued). "Notably, the effects of the GNB3 c.825C>T polymorphism on arterial hypertension among T-allele carriers are restricted to low renin levels." (PMID 36077181, 2022). "However, in comparison with the c.825C>T (rs5443) polymorphism of GNB3, the number of reports on the additional polymorphisms of GNB3 gene is low und the evidence of their contribution to the arterial hypertension, obesity and cardiovascular events is weak." (PMID 36077181, 2022). "Three hypertension susceptibility genes—AGT, CYP3A5 and GNB3—have been suggested to have undergone natural selection, providing a new way to study genetic susceptibility to hypertension." (PMID 33777100, 2021). "A case-control study in Taiwan showed that GNB3 C825T polymorphism might increase the risk of hypertension among individuals who consumed a high-sodium diet." (PMID 30857519, 2019). "Mutation in the GNB3 gene was accompanied by essential hypertension and obesity." (PMID 32231773, 2019). "In addition, our result suggested that gene–sodium interactions play an important role in the risk for developing hypertension i.e., participants with both GNB3 TT genotype and dietary high sodium are more susceptible to developing hypertension." (PMID 29848945, 2018). "Moreover, it has been observed recently that T allele carriers of GNB3 C825T are more susceptible to depression and hypertension." (PMID 27057160, 2016). "The human GNB3 C825T polymorphism accelerates intracellular information transfer, enhances the activity of intracellular sodium/hydrogen exchange, and increases the risk of hypertension and individual blood pressure-related organ damage." (PMID 24376503, 2013). "Since the GNB3 C825T polymorphism appears to be a useful marker to predict the relative risk of diseases, such as hypertension and stroke, this meta-analysis is better suited in a preventive aspect to identify certain genotypes that will be most likely to benefit from pharmacological interventions." (PMID 23799054, 2013). "The association between the GNB3 C825T polymorphism and hypertension among males and females." (PMID 23799054, 2013). "FTO protective haplotypes H2: CTGGC and H4: CTGAC interacted with GNB3 protective haplotype Ha: TC to contribute to 1.5- and 2.0-fold lower hypertension susceptibility than the individual protective haplotypes of either gene alone (P = 0.003; P = 6.86E–05, respectively)." (PMID 23691120, 2013). "Therefore, multiethnic studies with much larger sample-sizes are required to better evaluate the association between the GNB3 C825T polymorphism and hypertension or stroke." (PMID 23799054, 2013). "Therefore, we designed the present meta-analysis to better clarify the association between the GNB3 C825T polymorphism and hypertension or stroke." (PMID 23799054, 2013). "Thus, it seems that different automatic functions between genders altered the association of the GNB3 825T allele with hypertension." (PMID 23799054, 2013). "However, the present meta-analysis was designed to confirm the association between the GNB3 C825T polymorphism and essential hypertension or stroke." (PMID 23799054, 2013). "However, there were only two studies concerning an African population, thus a larger sample size is needed to further address the relationship between the GNB3 C825T polymorphism and essential hypertension in Africans." (PMID 23799054, 2013). "The widely accepted concept is that the GNB3 825T allele carriage results in hypertension." (PMID 22408428, 2012). "Meta-analyses addressing the role of the C825T polymorphism at the GNB3 locus in hypertension provide evidence for heterogeneity in the genetic effects across populations (i.e., effects found in different populations vary in a larger extent from what would be expected by chance alone)." (PMID 23056922, 2012). "Meta-analysis of the association between GNB3 gene C825T polymorphism and hypertension risk." (PMID 21364877, 2011).